BDNF (brain derived neurotrophic factor)
Diseases named in the same sentence as BDNF in open-access papers (continued):
Sharing a sentence is not in itself a finding about the gene and the disease.
peripheral nerve injury (47 papers, 2006 to 2024). Injury to a peripheral nerve. "In rats, nerve ligation (a model of peripheral nerve injury) increases brain-derived neurotrophic factor (BDNF), which causes a reduction in both mRNA and expression of the BK channel in the DRG, leading to an increase in excitatory transmission." (PMID 38584598, 2024). "The intrathecal administration of the TrkB-specific antibody K-252, a mechanical hyperalgesia in model rats, while reducing the expression levels of BDNF and TrkB, indicating that the BDNF–TrkB pathway is involved in neuropathic pain caused by peripheral nerve injury." (PMID 38989156, 2024). "The goal of this study was to determine whether the same neuronal BDNF-dependence underlies the effect of treadmill exercise on synaptic withdrawal following peripheral nerve injury." (PMID 25918648, 2015). "The BDNF‐Fyn‐GluN2B signaling cascade in the spinal dorsal horn may constitute a key mechanism underlying central sensitization and neuropathic pain development following peripheral nerve injury." (PMID 39648800, 2024). "After peripheral nerve injury, several neurotrophic factors, such as BDNF, GDNF, NGF, and neurotrophin-3, are synthesized and secreted by SCs to promote neuroregeneration." (PMID 37071193, 2023). "A previous study indicated that long-chain non-coding RNA MALAT1 was enhanced after peripheral nerve injury, which increased the expression and secretion of BDNF through sponging miR-129-5p, thus promoting proliferation and migration of Schwann cells." (PMID 35012663, 2022). "The complexity of excitatory synaptic connectivity and BDNF expression are reduced in the hippocampus after peripheral nerve injury, and the opposite changes depend on TNF‐α receptor 1 signaling." (PMID 34878231, 2022). "It has been reported that exogenously administrated BDNF in high doses of (20 μg versus 2 μg) can induce neuronal apoptosis at the site of peripheral nerve injury." (PMID 34948176, 2021). "In this study, we showed that BDNF derived from cortical microglia facilitates the maladaptive plasticity of cortical neurons after peripheral nerve injury." (PMID 34292944, 2021). "Peripheral nerve injury induced a remarkable enhancement of BDNF expression and possessed a regulatory activity on the occurrence and development of neuropathic pain." (PMID 32906633, 2020). "Major neurotrophic factors, such as IGF1, IGF2, NGF, BDNF, NT-3, and NT-4/5 can be produced by macrophages and are greatly upregulated in peripheral nerve injury, often concurrent with the influx of macrophages." (PMID 29907154, 2018). "It has been reported that the activation of the NR2B subunit was modulated by BDNF-TrkB signaling in the spinal dorsal horn following peripheral nerve injury." (PMID 28579944, 2017). "It has been established that activation of the BDNF-TrkB pathway in the spinal dorsal horn contribute to the central sensitization of peripheral nerve injury-induced neuropathic pain through microglial-neuronal activation." (PMID 28579944, 2017). "Since neurotrophic factors (including BDNF) can promote peripheral nerve regeneration, they are considered to hold great therapeutic potential for the treatment of peripheral nerve injury." (PMID 27381812, 2016). "We believe that they are strong evidence that motoneuronal BDNF is necessary for the effects of exercise on synaptic stripping following peripheral nerve injury." (PMID 25918648, 2015). "Treadmill exercise has a profound effect on synaptic inputs to motoneurons after peripheral nerve injury which requires BDNF production by those postsynaptic cells." (PMID 25918648, 2015). "This specific mechanism may involve the activation of P2X4 purinergic receptors (P2X4Rs) in microglial cells by ATP in the spinal dorsal horn following peripheral nerve injury, leading to BDNF release." (PMID 39648800, 2024).
peripheral nerve injury (continued). "It is hypothesized that BDNF synthesis is increased by activated microglia in the spinal cord after peripheral nerve injury and BDNF inhibits KCC2 expression after binding to TrkB receptors in the spinal cord." (PMID 36248405, 2022). "In addition, we found that microglia in the S1 up-regulate the expression of proinflammatory cytokines, including TNF-α, after peripheral nerve injury, and depletion of microglial BDNF prevents the increase of TNF-α." (PMID 34292944, 2021). "In addition, activation of P2X4 receptors leads to the release of BDNF from microglia after peripheral nerve injury." (PMID 29875666, 2018). "Consistent with a limited role of BDNF in pain-like behaviour under neuropathic conditions is the observation that the expression of BDNF is down-regulated in damaged nociceptive neurons following peripheral nerve injury." (PMID 30272037, 2017). "Therefore, we then studied the “loss of function” of the BDNF+/− mice and examined the effect of BMT from BDNF+/+ mice after peripheral nerve injury." (PMID 23028564, 2012). "Studies have shown that Shh is upregulated in Schwann cells adjacent to the injury site in the rat CCI model, which may promote axon regeneration and motor neuron survival after peripheral nerve injury by inducing the production of brain-derived neurotrophic factor." (PMID 39355777, 2024). "In the injured side of the DRG, pain-related signals including BDNF, COX2, and c-Myc were highly expressed in the control group after peripheral nerve injury, with percentages of 29.98% ​± ​3.79%, 26.75% ​± ​8.04%, and 22.94% ​± ​3.25%, respectively." (PMID 38368171, 2024). "Recent advances and pieces of evidence have made endogenous molecules like Brain-derived neurotrophic factor (BDNF) and pituitary adenylate cyclase-activating peptide (PACAP) the substance of choice for the therapeutic management of peripheral nerve injury." (PMID 34843075, 2022). "After peripheral nerve injury, NGF, BDNF, and NT3 are secreted and bind their high-affinity receptors trkA, trkB, and trkC and, then, activate the tyrosine kinase signaling system." (PMID 33447879, 2021). "The microglia activated by ATP also releases brain-derived neurotrophic factor (BDNF) on lamina I neurons that change the polarity of currents activated by GABA, a major effect after peripheral nerve injury." (PMID 33122991, 2020). "Interestingly, the neuronal shortage of BDNF is compensated by the microglia, which store BDNF in vesicles and release BDNF in response to increases in both primary afferent barrage and dorsal horn neuron activity when neuronal release of BDNF is impaired by a peripheral nerve injury." (PMID 30272037, 2017). "It has been shown, for example, that BDNF production actually increases in Schwann cells at the injury site or in DRG neurons themselves, in several models of peripheral nerve injury." (PMID 22253804, 2012). "Moreover, the expression of BDNF and Trkb were found to be significantly changed in DRG during inflammatory pain and in peripheral nerve injury models." (PMID 36818656, 2023). "The brain-derived neurotrophic factor, which plays a central role in neuronal development, maturation, and survival, may also be induced following ESWT as a treatment for peripheral nerve injury." (PMID 35630095, 2022). "Therefore, various neurotrophic factors, such as NGF, BDNF, and GDNF, have been used to enhance the repair outcomes of peripheral nerve injury." (PMID 33838005, 2021). "Previous studies on Slit focusing on SCs suggested that peripheral nerve injury could lead to the expression of various neurotrophic factors in SCs, including NGF, BDNF, neurotrophin 4/5, insulin growth factor 1 and 2, and Slit2 and Slit3." (PMID 31607866, 2019). "Firstly BDNF-induced changes in synaptic transmission and its lack of effect on the intrinsic excitability the cell bodies of lamina II neurons very much parallel those invoked by peripheral nerve injury." (PMID 37810432, 2023).
peripheral nerve injury (continued). "These actions are similar but not identical to those seen with BDNF or peripheral nerve injury." (PMID 37810432, 2023). "Nerve growth factor (NGF), glial cell line-derived neurotrophic factor (GDNF), brain derived neurotrophic factor (BDNF) and neurotrophin-3 (NT-3) have all been added to biomaterials to treat TBI as well as neurodegenerative disorders spinal cord injuries and peripheral nerve injuries." (PMID 26056586, 2014).
myocardial infarction (46 papers, 2010 to 2025). Gross necrosis of the myocardium, as a result of interruption of the blood supply to the area, as in coronary thrombosis. "Recently, the human BDNF Val66Met single nucleotide polymorphism has been associated with the increased propensity for arterial thrombosis related to acute myocardial infarction (AMI)." (PMID 32349267, 2020). "In conclusion, the BDNF Val66Met polymorphism predisposes to adverse cardiac remodeling after myocardial infarction in a mouse model and affects macrophage phenotype in both humans and mice." (PMID 32349267, 2020). "In patients with heart diseases, BDNF has proved to be a valuable cardioprotective factor against ischemic injury after myocardial infarction, and low BDNF levels were associated with worse prognosis in patients with heart failure and angina pectoris." (PMID 30133549, 2018). "History of myocardial infarction (MI) and carrying the rarer Met allele was associated with lower BDNF." (PMID 24670553, 2014). "Studies have shown that in the early stage of myocardial infarction, BDNF is increased in cardiomyocytes in the infarcted and peripheral regions." (PMID 38707889, 2024). "BDNF is involved in the process of cardiac structural and functional recovery during the acute and recovery phases of myocardial infarction." (PMID 38707889, 2024). "According to a recent in vivo study conducted on the hearts of WT mice exposed to myocardial infarction, BDNF levels increase within 24 h of MI and then fall at four weeks as LV dysfunction, adrenergic denervation, and impaired angiogenesis take place." (PMID 39766337, 2024). "It was also found that appropriate exercise during the recovery period of myocardial infarction can activate the BDNF-TrkB-FL-PI3K/Akt pathway to promote collateral angiogenesis and improve myocardial blood supply." (PMID 38707889, 2024). "Animal studies have shown that BDNF expression after myocardial infarction is upregulated by neuronal signaling from the heart to protect the myocardium from ischemic damage and thus exhibit a protective effect against cardiac remodeling." (PMID 38137853, 2023). "The interaction effect between the IL-18 and average BDNF methylation levels on composite MACEs (p = 0.019) and myocardial infarction (p = 0.027) was significant after adjusting for covariates." (PMID 36499595, 2022). "Subsequent to myocardial infarction, mechano- and chemo-sensitive information is transmitted through cardiac afferent fibers to the brain, which reacts by releasing BDNF into the blood stream—a scenario that is therefore designated as the ‘heart-brain axis’." (PMID 34572573, 2021). "Another indicated the involvement of the BDNF/TrkB pathway in the increased myocardial angiogenesis and improved cardiac function seen in rats the exercised after myocardial infarction." (PMID 33664650, 2021). "BDNF can promote young cardiac microvascular endothelial cells to migrate via the activation of the BDNF‐TrkB‐PI3K/AKT pathway after myocardial infarction." (PMID 32803867, 2020). "BDNF expression is probably upregulated by neural signals from the heart after myocardial infarction." (PMID 31284593, 2019). "With this approach, they demonstrated that conditional deletion of BDNF results in a reduced ejection fraction and an increased fibrotic area following myocardial infarction, suggesting that BDNF plays a cardioprotective role." (PMID 31105581, 2019). "One research group reported that BDNF protects from cardiac dysfunction after myocardial infarction." (PMID 30046375, 2018). "In one report, BDNF had a protective role in promoting cardiac remodeling after myocardial infarction." (PMID 26161003, 2015). "BDNF is involved in cardiomyocyte protection and cardiac remodeling after myocardial infarction." (PMID 38707889, 2024).
myocardial infarction (continued). "BDNF is associated with the pathogenesis of cardiovascular disease by the stimulation of atherogenesis and plaque instability via the stimulation of NAD(P)H oxidase and the inflammation after myocardial infarction." (PMID 37007871, 2023). "In addition, exercise can promote myocardial angiogenesis in mice with myocardial infarction by activating the BDNF-TrkB axis." (PMID 33584362, 2020). "In patients after myocardial infarction BDNF is related to inflammation and platelet activation." (PMID 31659205, 2019). "Moreover, BDNF concurs to increase factors that promote survival of cardiomyocytes and stimulate angiogenesis resulting in a decrease of remodeling of heart after myocardial infarction." (PMID 31284593, 2019). "In another study, microsphere mediated delivery of a combination of BDNF (25 μg) and bFGF (100 μg) was more efficacious as compared to bFGF alone (100 μg) in increasing blood flow and fractional shortening, in dogs following experimental myocardial infarction." (PMID 31105581, 2019). "In another report, BDNF negatively affected survival after myocardial infarction." (PMID 26161003, 2015). "BDNF is expressed in smooth muscle cells, macrophages and extracellular matrix of diseased cardiac tissue and pretreatment with BDNF can lead to increased myocardial injury in a rat model of myocardial infarction." (PMID 20404913, 2010). "BDNF may exert cardioprotective effects in the acute phase of myocardial infarction." (PMID 38707889, 2024). "Several previous studies firstly paid attention to theeffects of BDNF on myocardial infarction (MI)." (PMID 33477900, 2021). "To investigate whether plasma BDNF is associated with in vivo coronary plaque features, assessed by optical coherence tomography (OCT), in both acute myocardial infarction (AMI) and stable angina (SA) patients, we enrolled 55 CAD patients (31 SA and 24 AMI), and 21 healthy subjects (HS)." (PMID 34205863, 2021). "Furthermore, in mice, BDNF has been shown to have opposing roles following myocardial infarction." (PMID 26161003, 2015). "Treadmill exercise training increased BDNF and decreased Akt activity in the paraventricular nucleus post-myocardial infarction and protected against IFN-α-induced decreases in the expression of BDNF in the hippocampus and prefrontal cortex." (PMID 35821455, 2023). "In an acute myocardial infarction (AMI) model, rat cardiomyocytes transfected with miR-18a inhibitor were demonstrated to upregulate brain-derived neurotrophic factor expression, thus ameliorating cardiac ischemic injury and offering protection against AMI." (PMID 36140236, 2022). "TTC staining revealed that BDNF downregulation and inhibition of BDNF/TRKB binding diminished the effect of sh-G9a and increased myocardial infarct area in rats." (PMID 35439934, 2022). "Recent studies revealed that BDNF-TrkB pathway plays a critical role to maintain integrity of cardiac structure and function, cardiac pathology and regeneration of myocardial infarction (MI)." (PMID 36061561, 2022). "Brain-derived neurotrophic factor (BDNF) is the most important member of the neurotrophin family, which has also been shown to be involved in the physiopathology of cardiovascular conditions such as heart failure and myocardial infarction." (PMID 36078878, 2022). "BDNF triggers the activation of endothelial cells, vascular smooth muscle cells, and monocyte/macrophages, and promotes cardiac microvasculature development and dynamics, suggesting its important role in orchestrating the mechanisms of repair after myocardial infarction (MI)." (PMID 32349267, 2020). "Moreover, exercise training after myocardial infarction in male rats also induced BDNF in skeletal muscle and the non-infarct area of the left ventricle, which may contribute to improvement of muscle function as well as cardiac function." (PMID 35710575, 2022).
myocardial infarction (continued). "CSF BDNF values are discriminative between TBI fatalities and fatalities that died from diffuse cerebral hypoxia and acute myocardial infarction but not from isolated torso trauma." (PMID 35226180, 2022).